MTOR (mechanistic target of rapamycin kinase)
Diseases named in the same sentence as MTOR in open-access papers (continued):
Sharing a sentence is not in itself a finding about the gene and the disease.
cancer (continued). "Deactivating the mTOR pathway also inhibits cancer metastasis and invasion." (PMID 29266795, 2018). "Overwhelming evidences had demonstrated that VEGFA could bind to VEGFR2, then activate PI3K and its downstream target Akt and mTOR which play key roles in cancer proliferation, metastasis, angiogenesis, and survival." (PMID 30250022, 2018). "mTOR pathway inhibitors have been extensively developed for cancer chemotherapy." (PMID 29498706, 2018). "The PI3K/AKT/mTOR signaling pathway includes important transcriptional regulators in cancer cells." (PMID 29713287, 2018). "IFN-α signaling pathways include the classical JAK–STAT and other auxiliary pathways such as the PI3K/mTOR/AKT and MAPK-P38 axes, and dysfunction in signaling of PI3K/PTEN/AKT/mTOR, Wnt/GSK-3 and/or Ras/Raf/MEK/ERK axes is associated tightly with cancer progression and therapeutic resistance." (PMID 29587825, 2018). "mTOR is estimated to be aberrantly activated in over 70% of cancers." (PMID 29301334, 2018). "Alterations of mTOR signaling pathway have significant effects on cancer progression." (PMID 29666752, 2018). "However, PP242 and KU63794-induced ERK activation, and PP242 transiently inhibits mTOR signaling in some cancer cells." (PMID 29849119, 2018). "Accumulating evidence has shown that VEGFA could bind to its receptor VEGFR2, then activate PI3K and its downstream targets Akt and mTOR, which play crucial roles in cancer progression and survival." (PMID 30476901, 2018). "This study suggests at least that cancer patients treated with mTOR inhibitors do not experience adipose tissue loss." (PMID 30061533, 2018). "Down-regulation of CPT1C enhances the sensitivity to mTOR inhibitor, rapamycin in cancer cells." (PMID 29996946, 2018). "Besides the immunosuppressive role after solid organ transplantations or in the treatment of some cancers, another promising role of mTOR inhibitor as an antiaging therapeutic has emerged in the recent years." (PMID 30034573, 2018). "Currently several AKT inhibitors are under evaluation in clinical trials, while mTOR inhibitors such as temsirolimus and analogs have been approved by US Food and Drug Administration for the treatment of various cancers, which light hope for novel ones for AML treatment." (PMID 29997504, 2018). "GOLPH3 promotes growth factor-induced mTOR signaling in human cancer cells." (PMID 29996891, 2018). "When studied in combination, the inhibition of both PHGDH and p-mTOR in ECSLCs causes further augmentation of autophagy, and additionally promotes apoptosis, demonstrating the clinical applicability of PHGDH-based manipulations in cancer therapies." (PMID 30250195, 2018). "mTOR has recently been considered as an attractive target in cancer therapy." (PMID 29381751, 2018). "However, simultaneous MNK1/2 and PI3K/mTOR inhibition warrants further investigation as a therapeutic option for treating aggressive migratory cancers." (PMID 29581834, 2018). "Further study is needed to demonstrate how lipin‐1 modulates mTOR activity in cancer cells." (PMID 29659171, 2018). "The PI3K/AKT/mTOR pathway is frequently activated in cancer and maintains tumor growth." (PMID 29464099, 2018). "In addition to the significant role of mTOR in cancer progression, activation of mTOR downregulates autophagy." (PMID 29996471, 2018). "In a subset of clinical cancers, high IMPACT expression associated with decreased activity of pathways and genes involved in stress response and with increased activity of translational regulation such as the mTOR pathway." (PMID 30466445, 2018).
cancer (continued). "Similarly, our results showed that PCNP over-expression significantly induced apoptosis by inhibiting phosphorylations of PI3K (Tyr458/Tyr199), AKT (Ser473), and mTOR (Ser2448), suggesting that PCNP-associated agents can be developed as anti-cancer drugs." (PMID 29716528, 2018). "O-GlcNAcylation impacts PI3K/AKT and mTOR axis in cancer cells." (PMID 30356686, 2018). "However, high Rheb activity in many cancers leads to hyperactive mTOR signalling and increased HIF1 activity, resulting in the upregulation of VEGF and high vascularisation of the tumour." (PMID 30096787, 2018). "TQ was found to chemosensitize gemcitabine against cancer cells in inducing apoptosis by inhibition of Akt/mTOR/S6 signaling pathways and reduced expression of antiapoptotic proteins, providing a strong rationale for the potentiating role of TQ with gemcitabine in GBM therapy." (PMID 29651429, 2018). "Rapalogs can also cause activation of AKT through disruption of a negative feedback loop on the mTORC2 complex, which is involved in cancer cell growth and survival: this limitation led to development of a second generation of mTOR inhibitors, which are ATP-competitive mTOR kinase inhibitors." (PMID 29351204, 2018). "Recently, Akap1 has been shown to control mTOR regulating cancer cells growth." (PMID 29892230, 2018). "Similarly, drugs targeting mechanistic target of rapamycin (mTOR), a protein involved in nutrient sensing and metabolism regulation, are antiproliferative for many cancer cell lines, but have limited efficacy in treating mouse cancer models or patients." (PMID 30104199, 2018). "In addition, they also seem to induce autophagy in cancer cells by inhibiting hypoxia-inducible factor 1alpha (HIF1α), mammalian target of rapamycin (mTOR), and ERK1/2." (PMID 30373171, 2018). "Due to the positive outcome of these studies, the combination strategies with mTOR inhibitors and epigenetic drugs could be an innovative clinical approach in cancer therapy." (PMID 29351204, 2018). "Thus, prospective pro-senescent E6/E7 inhibitors would be expected to have therapeutic potential in normoxic cancer cells with elevated E6/E7 expression and active mTOR signaling." (PMID 29637045, 2018). "Amino acid transporters alanine-serine-cysteine transporter 2 (ASCT2) and L-Type Amino Acid Transporter 1 (LAT1) are coordinately enhanced in human cancers where among other roles, they are thought to drive mechanistic target-of-rapamycin (mTOR) growth signaling." (PMID 30029480, 2018). "We have proposed the questions on mTOR-dependent metabolism in cancer, which should be tackled in the future for achieving the goal of developing novel therapeutic and preventive strategies against cancer with facilitated metabolism." (PMID 30347859, 2018). "The risk of cancer development was not reduced by mTOR inhibitors (adjusted hazards ratio (HR) 0.80 (95% CI [0.60–1.09], p = 0.16))." (PMID 30473931, 2018). "mTOR plays a crucial role in normal physiology and in various diseases, including cancer; thus, understanding how mTOR signaling pathways work and developing agents that would interfere with its signaling for therapeutic purposes have been a main focus of research in the past 20 years." (PMID 29351204, 2018). "There is great interest in targeting mTOR signaling pathways as a therapeutic approach for several diseases such as autoimmune disease, chronic inflammation and allograft rejection, and as an adjunct to cancer therapy." (PMID 30532711, 2018). "Abnormal activation of the PI3K/Akt/mTOR pathway is frequently observed in various types of human cancers and therefore targeting this pathway might represent a key therapeutic opportunity for the treatment of tumor." (PMID 29898734, 2018).
cancer (continued). "Numerous studies have hence been carried out investigating the interaction between PI3K or mTOR inhibitors and cisplatin, which in fact have displayed a synergistic anti-tumor effect in chemo-naive or resistant cancers, e.g. melanoma, breast, lung and nasopharyngeal cancers." (PMID 29642900, 2018). "This mTOR stimulation sensitized cancer cells to mTOR inhibitors such as everolimus." (PMID 29882812, 2018). "PI3K/Akt/mTOR pathway can be used as a target for cancer therapy." (PMID 29570613, 2018). "Inhibitors of mTOR downstream targets, like S6K, also presented positive effects against cancer." (PMID 29805774, 2018). "A study is needed to evaluate the specific changes of mTOR activity in the brain as a consequence of chronic pain, but different types of pain – cancer, inflammatory and neuropathic – should be evaluated because the role of mTOR is likely to be different depending on the underlying cause(s) of pain." (PMID 31194026, 2018). "Bi-directional mKitL–c-Kit signaling may therefore contribute to the interaction between cancer cells (including cancer stem cells) and stromal cells that generates reactive stroma through Akt/mTOR pathway activation." (PMID 30410062, 2018). "mTOR is referred to as a master regulator of cell growth control and is often activated in cancer." (PMID 29301334, 2018). "Cell growth is regulated by mTOR, the overactivation of which induces cancer progression." (PMID 29434323, 2018). "Specifically, a large quantity of data points to the role of mTOR activation in cancer development through protein-induced IGF-1 signaling and to the beneficial effects of caloric and protein restriction not only on aging-associated diseases such as cancer but also on life span." (PMID 30363988, 2018). "Cancer cells are often capable of surviving in abnormal and harsh conditions such as hypoxic and low nutrient conditions and therefore may have altered mTOR regulators or a shift in dependence on the PI3K/AKT/mTOR pathway." (PMID 29518028, 2018). "The Akt/mTOR signaling cascade could thus be a target of adjunct anti-cancer therapy whereby using Akt or mTOR inhibitors could hinder disease progression and dissemination while undergoing radio and/or chemotherapy, thereby greatly improving prognosis." (PMID 30323898, 2018). "Neither high- nor low-dose of mTOR inhibitors was associated with a reduced risk of cancer or of all-cause mortality." (PMID 30473931, 2018). "Recent studies have shown that aspirin inhibits mTOR signaling by activating AMPK in cancer cells." (PMID 28525374, 2017). "Thus, in addition to PML NB-mediated nuclear retention of mTOR and inactivation of AKT, we have uncovered a novel mechanism by which PML NB loss contributes to mTOR activation in cancer via dysregulation of DDIT4 gene expression." (PMID 28332630, 2017). "The mechanistic target of the rapamycin (mTOR) pathway is frequently activated in human cancers." (PMID 29137436, 2017). "In up to 80% of human cancers, mTOR is aberrantly activated." (PMID 28409158, 2017). "The inhibition of PI3K/AKT/mTOR pathway could, therefore, provide a suppressive measure against cancer." (PMID 28490807, 2017). "Until now, there has been no published work on the association between MTOR: rs2536 and cancer outcomes." (PMID 28280736, 2017). "However, the role of mTOR inhibitors in patients who developed post-transplant cancers is less certain." (PMID 28160552, 2017). "Various types of human cancers exhibit aberrancies in the PI3K/Akt/mTOR signaling pathway; therefore, this pathway might be a useful clinical target for cancer treatment." (PMID 28977849, 2017).
cancer (continued). "In addition, upon glucose deprivation, treatment with α-KG derivatives and its reduced form 2-hydroxyglutarate (2-HG) has revealed the ability to inhibit the ATP synthase, resulting in mTOR signaling reduction and autophagy blockage in cancer cells." (PMID 28184304, 2017). "Here, we show that REP1 plays a crucial role in regulating mammalian target of rapamycin (mTOR) signaling and its downstream pathways, as well as autophagy and macropinocytosis, which are essential for cancer cell survival during metabolic stresses including starvation." (PMID 28846638, 2017). "However, other reports showed that mTOR activation induces tumor suppressors that inhibited cancer cell proliferation." (PMID 29137114, 2017). "Several preclinical studies have reported potential therapeutic tools for the treatment of human cancers, that target the translation machinery, such as mTOR inhibitors (e.g., Rapamycin, Torin 1), eIF4E inhibitors (e.g., 4EGI-1, 4E1RCat), and MNK inhibitors (e.g., Cercosporamide, CGP57380)." (PMID 28961193, 2017). "However, miR-221 can also specifically promote cancer cell proliferation through modulation of the mTOR (mammalian target of rapamycin) pathway." (PMID 28474282, 2017). "Recent findings suggest that dual targeting of PI3K and mTOR has the ability to overcome resistance to IR and improve the anticancer efficacy of the treatment in various cancer cell types in vitro and in in vivo xenograft models of cancer." (PMID 28978144, 2017). "Nevertheless, AMPK/mTOR pathway has been concerned in cancer by a lot of investigators because it controls many oncogenic protein transcription and translation, highlighting that AMPK, an important energy regulator, was an emerging target for inhibition of the mTOR pathway in cancer." (PMID 28061838, 2017). "In addition to PD-1/PD-L1 signaling-mediated effects on the TILs, PD-L1 expression on the cancer cells has been shown to mediate cell-intrinsic signaling through PI3K/Akt/mTOR pathway leading to enhanced glycolysis in the cancer cells." (PMID 28447025, 2017). "While these data suggest a potential beneficial role for mTOR inhibitors, it is important to mention that in many cancer settings the use of some inhibitors of the PI3Ks-dependent pathways has unfortunately led to the discovery of compensatory mechanisms that reduce their therapeutic efficiency." (PMID 28696382, 2017). "MiRNA-100 could suppress the related proteins of the IGF/mTOR signaling cascade in different cancers." (PMID 28977982, 2017). "Cancer cell proliferation, survival, and growth required the activation of mTOR signaling." (PMID 28406985, 2017). "We speculated that PI3K-Akt-mTOR-p70S6K1 pathway might be a novel target for cancer treatment research." (PMID 28532456, 2017). "PI3K/AKT/mTOR pathway plays a significant role in the growth and survival of various cancer cells." (PMID 26988754, 2017). "Moreover, both ERK1/2 and mTOR/S6 signaling were involved in the suppression of proliferation, migration and invasion of cancer cells induced by SYK." (PMID 29137391, 2017). "Furthermore, since it has been shown that HSF1 and the AKT/mTOR cascade functionally interacts in other cancer types, we determined the levels of AKT and mTOR activity and correlated them with HSF1 activity in human HCC specimens (n = 64)." (PMID 28903330, 2017). "The PI3K/AKT/mTOR pathway, which is activated in cancer, is an important factor in autophagy." (PMID 29340076, 2017). "mTOR inhibition, on the other hand, could then lead to feedback activation of autophagy, which reportedly counteracts the anti-cancer activity by a number of mTOR inhibitors." (PMID 29228741, 2017).
cancer (continued). "Interestingly, serum collected 24 h post-exercise had a similar inhibitory effect on cancer cell survival, Akt, mTOR, p70S6K, and Erk phosphorylation, as serum collected 5 min and 1 h post-exercise." (PMID 28481292, 2017). "In addition, GOLPH3 was found to be involved in the growth, differentiation and proliferation of cancer cells via mammalian target of rapamycin (mTOR) signaling." (PMID 28801637, 2017). "In the following experiments, we asked whether BICA could recapitulate the cancer–niche interaction observed in whole animals by pharmacological or genetic perturbations of the heterotypic adherens junctions–mTOR pathway in both BICA and IVBL." (PMID 28429794, 2017). "In addition to its effects in cancer cell proliferation, the mTOR pathway plays an essential role in cancer formation." (PMID 28891980, 2017). "This led to the discovery of substituted 6-aminoheterocyclic 2, 4-bis morpholino pyrimidines, of which the highest soluble and the most potent compound was compound 90 (NVP-BKM120, PI3Kα IC50 ~ 30nM, mTOR IC50 ~ 4600nM) that has entered into Phase II clinical trials for the treatment of cancer." (PMID 27769061, 2017). "As Akt-mTOR pathway regulates cancer cell migration and invasion, we investigated whether the combined treatment impacts cell motility using wound-healing assay." (PMID 27154770, 2017). "Additionally, the PI3K/AKT/mTOR pathway plays an important role in the resistance to a number of anti-cancer agents." (PMID 28524116, 2017). "Unfortunately, however, hypoxic HPV-positive cancer cells would be expected to resist a pro-senescence therapy that is based on E6/E7 inhibition, since the expression of the therapeutic targets is blocked and pro-senescent mTOR signaling is impaired." (PMID 28678198, 2017). "Indeed, several reports have shown that small molecules targeting the mTOR-4EBP1-eIF4E axis reduces cancer growth in many experimental models." (PMID 28961193, 2017). "Activated AMPK could phosphorylate tumor suppressor tuberous sclerosis complex 2 (TSC2) to inhibit mTOR activity, which plays a critical role in cancer progression." (PMID 28271076, 2017). "Mammalian target of rapamycin (mTOR), a downstream protein of the PI3K/Akt pathway, is activated by growth, changes in nutrient and energy levels, and hypoxia, and has also been implicated in cancer cell proliferation and survival." (PMID 29162840, 2017). "Our findings indicate that Snail expression may serve as a predictive marker for mTOR-targeted therapies in cancer." (PMID 29263324, 2017). "KRAS mutations, identified in approximately 30% of human cancers, may be associated with resistance to PI3K/AKT/mTOR inhibitors." (PMID 28945763, 2017). "Therefore, the inhibition of the PI3K-Akt-mTOR pathway can effectively suppress the occurrence and development of cancer." (PMID 28218676, 2017). "Blockade of AKT/mTOR signaling pathway has been considered to be useful in cancer treatment." (PMID 28427191, 2017). "The PI3K/AKT and mammalian target of rapamycin (mTOR) pathways are not only commonly regarded as a single overlapping pathway but are also crucial regulators of growth, survival, proliferation, and metabolism of cancer cells." (PMID 28607534, 2017). "Therefore, further evaluation of the mTOR signaling in human cancers is important for development of anti-neoplastic therapy targeting the mTOR signaling pathway." (PMID 28811537, 2017). "Notably, p62 is known to regulate nuclear factor (erythroid-derived 2)-like 2 (NRF2), mTOR, and NF-kB, which are paramount for cancer cell survival." (PMID 29088798, 2017). "In this study, to explore the potential role for mTOR signaling in the regulation of RNR in cancer cells, we have determined the mRNA and protein levels of RRM1 and RRM2 in cell culture and mouse tumor xenografts following pharmacological and genetic inhibition of mTOR signaling." (PMID 28507282, 2017).